CD4 (CD4 molecule)
Diseases named in the same sentence as CD4 in open-access papers (continued):
Sharing a sentence is not in itself a finding about the gene and the disease.
melanoma (continued). "Interestingly, evidence for the therapeutic efficacy of adoptively transferred CD4+ T cells in the clinical setting was provided in melanoma already in 2008." (PMID 37965314, 2023). "Furthermore, CPI-613–pretreated Lal–/– CD11c+ cells showed reduced capabilities of T cell suppression when cocultured with CD4+ T cells in vitro and tumor growth stimulation when coinjected with B16 melanoma cells subcutaneously in Lal+/+ mice." (PMID 35917184, 2022). "Similarly, in vitro OX40 engagement by three patient-derived tumour-specific CD4 T-cell lines exhibited heightened cytolytic effects against melanoma cell lines, arguing for in vivo tumoricidal capacity, as observed in the preclinical evaluation." (PMID 35572552, 2022). "The combination of BRAF and MEK inhibitors was shown to induce pyroptosis in melanoma cells via GSDME which resulted in an increase in CD4+ T cell and CD8+ T cell infiltration and a decrease in myeloid-derived suppressor cells (MDSCs) and tumor-associated macrophages (TAMs)." (PMID 36605187, 2022). "Immune-profiling and cell depletion experiments revealed that melanoma cell-derived Activin-A reduces the dependence on suppressive CD4+ T cells to escape immune surveillance, correlating with the diminished secretion of specific chemokines such as CXCL9 and CXCL10." (PMID 35580932, 2022). "In addition, it has been observed in melanoma patients that CD4 + T cells expand after PD-1 blockade and that activated CD4 + T cells secrete IFN- γ and chemokines, which contribute to antitumor immunity." (PMID 35874717, 2022). "Although it is difficult to decipher this alteration and the exact mechanism cannot be determined, we suspect that it represents a stabilization mechanism that CD4+CD25+ T cells use in patients with melanoma; the PD1/PDL1 axis is used by regulatory-T cells to suppress autoreactive-B cells in vivo." (PMID 35954454, 2022). "We have previously reported that GILT expression could significantly improve CD4+ T cell recognition of human melanoma cells." (PMID 35162988, 2022). "Indeed, the engagement of OX40, a costimulatory molecule expressed primarily on activated CD4+ T cells, induces tumor-specific CD4+ T cell population able to eradicate advanced melanomas in mice and also human melanoma cells in an in vitro model." (PMID 35008422, 2022). "This peptide is detected by mass spectrometry in B16 melanoma grown in vivo and citrulline specific CD4 responses to two peptides spanning this epitope mediate efficient therapy of established B16 melanoma tumours in HHDII/DP4 (p<0.0001) transgenic mouse model." (PMID 36544781, 2022). "Moreover, in recent melanoma clinical trials, neoantigen vaccination induces CD4+ T cell responses and improves patient survival (NCT02035956, n = 15), (NCT02287428, n = 56)." (PMID 35008422, 2022). "GILT appears to play a role in Ag cross-presentation by dendritic cells for epitopes recognized by CD8+ T cells, but in the case of CD4+ T cell responses to melanoma, cells as well as APC expressions of GILT may impact tumor clearance." (PMID 35162988, 2022). "However, the frequency of CD4+ MAIT cells as a proportion of MAIT cells was increased in melanoma patients than HD." (PMID 35028137, 2022). "Our findings confirmed previous results that describe functional correlations of melanoma-specific CD4+ T cells, macrophages and dendritic cells with cancer phenotypes, suggesting that these cells may be used to alter the tumor microenvironment." (PMID 36713580, 2022). "Moreover, CD4-positive T cell clones in peripheral blood proliferate in melanoma patients after treatment with an anti-CTLA-4 antibody, and these CD4-positive T cell clones are enriched in corresponding tumors." (PMID 36361781, 2022). "With regard to CD4+T cells, B-cells and mast cells, their specific roles in the melanoma immune microenvironment remain unclear." (PMID 36513682, 2022).
melanoma (continued). "The NDV infection of human melanoma cells could break the tolerance of a melanoma-specific CD4+ T helper cell line." (PMID 35327364, 2022). "Additionally, inhibiting VPS34 induces the infiltration of NK, CD8+, and CD4+ T cells in melanoma and colorectal cancer." (PMID 36034776, 2022). "Despite their expression of these HLA molecules, melanoma cells often inefficiently process and present Ags to CD4+ T cells, which may contribute to their immune evasion." (PMID 35162988, 2022). "NDV infection of human melanoma cells could break tolerance of a melanoma-specific CD4+ T helper cell line." (PMID 36361831, 2022). "The results revealed that B cells, pro B cells, CD4+ T cells, M1 macrophages, mast cells, Th2 cells, cDCs, pDCs, NK cells, and monocytes, were found to be associated with the PGS score in melanoma and show a significantly higher prevalence in the PGS-low group." (PMID 36513682, 2022). "Similarly, ACT of naïve tumor-specific CD4+ T cells along with CTLA-4 blockade led to regression of large B16 melanomas, and the transferred CD4+ T cells developed cytotoxic activity." (PMID 36159781, 2022). "The whole-cell vaccine optimized by CpG/αOX40/cGAMP can fully mobilize the immune system and increase the infiltration of lymphocytes (especially CD4+ T cells) within the tumor, thus significantly preventing the growth of melanoma and prolonging the survival time of melanoma mice." (PMID 35748951, 2022). "Indeed, complete melanoma regressions have been observed following infusion of antigen-specific CD4+ T cells." (PMID 35008422, 2022). "On the mRNA level, regressed melanomas showed a higher CD4 and CD8 expression." (PMID 35463364, 2022). "Besides, Binnewies and collaborators observed, in a murine model of melanoma, that the depletion of regulatory T cells into the tumoral site induced a cDC2 increase activity in eliciting intra-tumoral CD4+ T cell responses with subsequent tumor growth control." (PMID 35757002, 2022). "Notably, Tirosh and colleagues also conducted scRNA-seq on tumour-infiltrating lymphocytes (TILs) collected from 15 melanomas, where they observed heterogeneous activation states of T cells within CD4+ and CD8+ populations." (PMID 35740696, 2022). "In addition, recent reports have shown that systemic CD4+ T cells influence positively ICI outcomes and that a repertoire of pre-existing blood CD4+ T cells predicts better clinical outcomes in melanoma patients treated with anti-CTLA-4." (PMID 35008422, 2022). "Helper CD4+ T cells involve the activation and expansion of adaptive immune cells in melanomas." (PMID 35248056, 2022). "The effectiveness of immune checkpoint blockade therapy demonstrates that melanoma cells express antigens that can be recognized by CD4 and CD8 T cells, and also that T cell responses to those antigens can mediate tumor regression, when tumor-associated immune dysfunction is abrogated." (PMID 36176766, 2022). "Using blood samples from melanoma patients who had previously been vaccinated with a 6MHP vaccine on the Mel41 trial and had developed a robust CD4+ T cell immune response to the TSY antigen, we analyzed lymphocyte viability and CD4+ T cell proliferation to the TSY nano-formulations ex vivo." (PMID 36176766, 2022). "IFNγ could upregulate the expression of MHC-II on B16 cells, which augmented CD4+ T cell-mediated killing of melanoma." (PMID 36733396, 2022). "These miRNAs, including hsa-let-7c-5p, hsa-miR-130b-3p, and hsa-miR-142-3p, and activated dendritic cells, naïve CD4 T cells, M1 macrophages, and plasma cells may play vital roles in the pathogenesis of melanoma." (PMID 35903462, 2022). "It will be interesting to understand how the Treg may control cDC2 function and influence the anti-tumor CD4+ T cells response, both in melanoma and in other tumors." (PMID 35757002, 2022). "The increase in central memory CD4 T cells in peripheral blood might be used to predict the clinical response of patients with malignant melanoma to PD-1-blocking therapy." (PMID 36005189, 2022).
melanoma (continued). "In the co-culture assays, we evaluated the potential of melanoma patient B cells to mediate modulation of autologous CD4+ T-helper cell phenotype and functions, including the modulation of T cell proliferation, TNF-α, IFN-γ, and FOXP3 expression and induction of FOXP3+ Tregs." (PMID 35909944, 2022). "Additionally, CD4+ T cells have been shown to promote the differentiation of effector CD8+ T cells in a mouse melanoma model known to be immunogenically cold and poorly responsive to immune checkpoint blockade." (PMID 35565302, 2022). "We hypothesized that CD4+ T cells would be required for synergy with CDDO-Me, as CD4+ Th1 cells have been implicated in TAM redirection in B16 mouse melanoma models." (PMID 35265066, 2022). "We have previously developed a multi-peptide melanoma vaccine consisting of 6 melanoma helper peptides (6MHP) designed to induce melanoma-reactive CD4+ T cells, and found that they are immunogenic in humans, inducing objective clinical responses and very high rates of 5-year survival." (PMID 36176766, 2022). "We examined melanoma patient-derived B cells in B:T-helper cell ex vivo co-cultures to evaluate whether these supported induction of FOXP3+ CD4+ regulatory T cells (Tregs)." (PMID 35909944, 2022). "Tumor cells could also present MHC class-II epitopes of NY-ESO-1 on their surface, and NY-ESO-1 specific CD4 T cells were previously demonstrated to induce tumor regression in melanoma patients." (PMID 33717196, 2021). "Frequent recognition of neoantigens by CD4+ TH1 cells have been reported in melanoma as well." (PMID 34012451, 2021). "Furthermore, CD40 was shown to co-stimulate both anti-CD3-triggered CD4+ and CD8+ human T cells and enhance melanoma cell susceptibility to T cell lysis." (PMID 34092233, 2021). "As a result, intratumoral injection of either autologous CD8+ T-cell melanoma antigen-activated by gp100-pulsed Flt3L-DCs or autologous CD4+ T cells activated by tumor lysate-pulsed Flt3L-DCs failed to mediate any measurable antitumor activity against pre-established B16F1 in B6 mice." (PMID 34625113, 2021). "The many roles of G9a, from the repression of stem cell factors in early development and CD4 during CD8+ T cell differentiation to inhibiting the DKK1 repression of Wnt signal in melanoma, highlight the broad range of functions that are controlled by the epigenetic regulation of histone methylation." (PMID 34691767, 2021). "In recent years, the antitumor role of CD4+ T cells has gained greater interest since several melanoma (neo)antigens were found to be recognized by CD4+ T cells both in murine models as well as in human melanomas." (PMID 34072260, 2021). "One of the earliest reports involved selection and expansion of clonal autologous CD4+ T cells from a melanoma patient recognizing an epitope from a shared cancer-testis antigen (NY-ESO-1) presented in the context of HLA-DPB1*0401; infusion of these cells led to a long-term complete response." (PMID 34910940, 2021). "In addition, M1 macrophage, NK, CD8+, and CD4+ T cells are indicated to benefit the survival of melanoma patients, warranting further investigation regarding the precise underlying mechanism." (PMID 33868993, 2021). "In addition, this group also found an analogous population of CD4+ T cells in the peripheral blood of melanoma patients who had received ipilimumab (α-CTLA-4 blocking antibody) combined with granulocyte-macrophage colony-stimulating factor (GM-CSF) therapy." (PMID 32457487, 2021). "In addition PD-L1/PD-1 co-expressing CD4+ T-cells in blood tend to be related to a lower TILs score at the level of tumor micro-environment in our melanoma cohort." (PMID 34071888, 2021). "The authors considered the hypothesis of CD4+ lymphocytes phagocytosis by melanoma tumor cells with resulting immunoreactivity or even the possibility of an artifactual cross-reactivity due to endogenous Fc receptor expression by tumor cells." (PMID 34449584, 2021).
melanoma (continued). "Concomitant antigen-specific CD8 and CD4 T cell responses were also observed upon vaccination with the Melan-A26–35 peptide that triggered a switch from Treg to Th1 polarized tumor-specific CD4 T cells in HLA-DQ6-vaccinated melanoma patients." (PMID 34064410, 2021). "MSCs intravenously injected 24 h after melanoma induction significantly enhanced the cytotoxicity of CD8+ CTLs and NK cells, increased the production of anti-tumorigenic cytokines (TNF-α, IFN-γ, IL-17) in tumor-infiltrated CD4+ Th1 and Th17 lymphocytes and attenuated melanoma growth and progression." (PMID 34830312, 2021). "A very recent report of melanoma treatment-related immune monitoring showed that PD-1 downregulation on CD4+CD25+CD127−PD1+ regulatory T lymphocytes under PD-1 inhibitor treatment was observed only in patients with favorable prognosis but not in patients with unfavorable prognosis." (PMID 34360781, 2021). "The presence of TLS in human melanoma samples further correlates with increased frequencies of switched memory B cells, plasmablasts/plasma cells and less exhausted, activated memory-like CD4+ and CD8+ T cells as well as with response to ICB therapy." (PMID 34248957, 2021). "Similarly, single-cell RNA-sequencing analysis conducted on advanced melanoma biopsies showed that ICI responders had a higher content of memory CD4+ T cells at baseline." (PMID 34220837, 2021). "Additionally, we revealed that the fractions of CD8+ T cells, Tfh cells, activated memory CD4+ T cells and M1 macrophages were associated with a favorable response, PFS and OS after ICI therapy in melanoma and urothelial cancer." (PMID 34220837, 2021). "Nevertheless, a small study in melanoma designed personalised neoantigen-based peptide vaccines for six patients, which led to the generation of tumour-specific CD4+ and CD8+ T lymphocyte responses and clinical benefit (four out of six patients remaining cancer free at a 25-month follow up)." (PMID 33918976, 2021). "Both CD8+ and CD4+ T cells represent the most prevalent immune-infiltrating populations found nearby melanoma cells, but recent studies revealed that other types of immune cells, such as M1 or M2 macrophages, also correlate with melanoma prognosis." (PMID 34066146, 2021). "In a variety of cells ranging from epithelial cells, macrophages, and CD4+ T cells to cells from tumors, such as myeloma, pancreatic cancer, and melanoma, membrane CD138 is cleaved by different proteinases, such as MMP9, MT1-MMP, MT3-MMP, collagenase, and trypsin." (PMID 34364875, 2021). "Interestingly, in melanoma CD4+ T cells, exhaustion was found to be related to the kynurenine pathway and IDO1 overexpression." (PMID 34439305, 2021). "The earliest reports that CD4+ T cells could be directly cytotoxic to patient tumor cells involved isolation of circulating CD4+ T cell clones specific for NY-ESO-1 in melanoma patients treated with ipilimumab (anti-CTLA-4)." (PMID 34910940, 2021). "The frequency of CD4/CD8 DP T cells was significantly increased in melanoma." (PMID 34095321, 2021). "Similarly, enrichment of CD8+NKG2D+ effector T cells and decrease in CD4+CD25+FOXP3+ Tregs were observed in B16 melanoma as well as NBL tumors." (PMID 34721405, 2021). "Similarly, protein expression of CCR8 in human NSCLC and melanoma tumors was restricted to the activated (OX-40+) CD3+CD4+CD127−CD25+ ti-Tregs." (PMID 33589525, 2021). "Tagln2−/− DCs exhibited significant defects in their abilities to home to draining LNs and to form optimal contacts with cognate CD4+ T cells to prime T cells, and these changes were associated with a failure to suppress tumor growth and metastasis of B16F10 melanoma cells in mice." (PMID 33731208, 2021). "Whether CPI also recruits CD4+ CTLs is not yet known, but the expansion of NY-ESO-1 specific, EOMES+ CD4+ T cells able to lyse autologous tumor cells in a MHC-class II restricted manner was described in melanoma patients after Ipilimumab infusion." (PMID 33546283, 2021).
melanoma (continued). "Moreover, memory env-reactive CD4+ T cells, generated by B3-Ab:env123–139 immunization, were highly effective in rejecting B16-Ab:env123–139 melanoma cells, indicating that Ab:env123–139 complexes expressed in B16 cells can be recognized effectively." (PMID 32313208, 2021). "Interestingly, depletion of STAT3 in the preclinical model dampened the tumor growth and Treg cells recruitment and increased the CD8+/CD4+ ratio in melanoma." (PMID 33936081, 2021). "Especially in the treatment of HBV-induced HCC, their role may even be beneficial, as, for example, CD4+ T cells with cytotoxic activity were shown to induce tumor rejection in a melanoma model." (PMID 34853796, 2021). "Moreover, we analyzed the expression level of gene CD3E, CD4, CD8A, GZMB, NKG7, TCF7 and TRBC2, the well-known markers for CD8+ T cells, and they were all shown to have significantly higher expression level in melanoma patients with low risk." (PMID 34040608, 2021). "Furthermore, after adoptive transfer of PCK1-overexpressing CD4+ or CD8+ T cells into a melanoma-bearing mice, there was a decrease in tumor growth which prolonged survival of the mice." (PMID 34079545, 2021). "In contrast a higher frequency of PD-1/PD-L1 expressing non-proliferating (Ki67−) CD8+ and CD4+ T-cells before treatment was associated with worse outcome in melanoma." (PMID 34071888, 2021). "Previously, we showed that Stat3 deletion in moDCs used as a tumor vaccine enhances accumulation of effector CD8+ and CD4+ T cells, and suppresses FoxP3+ CD4+ T cell (Treg) accrual in melanoma tumors, correlating with decreased tumor growth and increased mouse survival." (PMID 31947933, 2020). "Finally, after treatment with anti-CTLA4 therapy, the levels of circulating CD33 + CD11b + HLA-DR- myeloid derived suppressor cells correlated with survival in melanoma patients, as well as distinct CD4+ and CD8+ memory T cell subsets." (PMID 32460897, 2020). "Both IFN-γ/IL-10 mRNA ratio and CD4 + subpopulations ratio in PBMCs could predict response to anti-PD-1 in immunotherapy-naive melanoma patients." (PMID 33077770, 2020). "A recent study showed that the enrichment of the feces with C. aerofaciens and B. longum in melanoma patients, who received anti-PD1 treatment, is associated with an increased frequency of CD8+ T cells and reduced Foxp3+CD4+ Tregs in the tumor microenvironment." (PMID 32295112, 2020). "Additionally, TLR7 activation in melanoma is associated with significant increases in: intratumoral CD8+ T and CD4+ T cells; anti-tumor macrophages, B cells, IFNγ, IFNα/β, and plasmacytoid dendritic cells, and pro-inflammatory cytokines IL6 and IL12." (PMID 32455916, 2020). "GJIC is also involved in antigen presentation through direct coupling between monocytes and DCs, between DCs, between tumor cells and endothelial cells, and at the immune synapses formed between melanoma cells and CD4+ T cells, melanoma cells and natural killer (NK) cells, and DCs and CD4+ T cells." (PMID 33321749, 2020). "Thus, similar to our animal experiments, a combination therapy in melanoma patients led to the expansion of effector CD4+ and CD8+ T cells showing enhanced production of granzymes." (PMID 32226027, 2020). "Indeed, our data evidenced a significant accumulation of circulating NK cells and single positive CD4 or DP T cells in very young melanoma bearing pigs." (PMID 32180771, 2020). "Moreover, an enhanced frequency of melanoma-infiltrating ICOS+ CD4+ T cells, sustained over 3 months of anti-CTLA-4 treatment, was associated with better OS." (PMID 32194568, 2020). "Similarly, NY-ESO-1-specific CD4+ T cells isolated from melanoma patients are able to lyse melanoma cells expressing the cognate antigen." (PMID 31924474, 2020). "Interestingly, 3–4 week-old melanoma-bearing pigs harbored higher proportions of NK cells and single positive CD4 or DP T cells and lower proportion of B cells, eosinophils and γδ T cells compared to age-matched healthy pigs." (PMID 32180771, 2020).